APP (amyloid beta precursor protein)
Diseases named in the same sentence as APP in open-access papers (continued):
Sharing a sentence is not in itself a finding about the gene and the disease.
Cognitive impairment (continued). "The upregulation of Klotho levels in the brain and serum significantly ameliorated Aβ burden, neuronal and synaptic loss and cognitive deficits in aged APP/PS1 mice." (PMID 32964663, 2020). "This suggested that long-term treadmill exercise improved APP/PS1 mutation-induced cognitive defects by partially reversing aberrant neuronal activity and/or seizures, which was probably associated with the recovery of hippocampal Nav." (PMID 32256560, 2020). "C3 deficiency ameliorates age-dependent loss of synapses and neurons, and cognitive deficits in aged APP/PS1 mice although it increases cerebral Aβ deposits." (PMID 32391019, 2020). "In conclusion, our results confirm that a diet regimen with additional choline throughout life can reduce the pathological burden and associated cognitive deficits seen in female APP/PS1 mice." (PMID 31560162, 2019). "Our results illustrate that a lifelong regimen of additional choline produces significant benefits on AD‐like pathology and associated cognitive deficits in female APP/PS1 mice." (PMID 31560162, 2019). "Here we show, in a mouse model, that triplication of chromosome 21 genes other than APP increases amyloid-β aggregation, deposition of amyloid-β plaques and worsens associated cognitive deficits." (PMID 29945247, 2018). "To date, multiple transgenic mouse models overexpressing human APP with familial AD mutations have been shown to develop age-dependent Aβ amyloidosis, neuroinflammation, and cognitive impairments in spatial memory and contextual fear memory." (PMID 30055565, 2018). "Intracerebroventricular administration of APP was shown to ameliorate both motor and cognitive deficits, as well as attenuate cellular loss and inflammation following TBI in vivo." (PMID 29320530, 2018). "For example, MgT treatment was reported to stabilize β-secretase (BACE-1) expression and to reduce soluble APP and β-C-terminal fragments, which prevented and reversed cognitive deficits and synaptic loss in APP/PS1 transgenic mice." (PMID 29899688, 2018). "Together, our findings suggest new AD risk factors and therapeutic targets, as well as a novel putative function for APP and its role in ciliopathy-associated cognitive impairment." (PMID 30140428, 2018). "In humans, an ADAMTS9 gene variant is associated with type 2 diabetes (T2DM) is most frequently linked with aging, cognitive impairment, AD-associated neuronal APP-Aβ deposits." (PMID 28373841, 2017). "We investigated network hypersynchrony at 3 weeks of age (prior to amyloid plaque deposition, neurofibrillary pathology, and cognitive impairment) in a triple transgenic mouse model of AD (3xTg-AD) that harbors mutated human APP, tau and PS1 genes." (PMID 28392767, 2017). "We previously found that a mutation in APP that prevents this caspase cleavage ameliorated synaptic loss and cognitive impairment in a murine AD model." (PMID 28261092, 2017). "Several human studies have linked APP over-expression and alterations in APP processing to synaptic dysfunction and/or cognitive deficits." (PMID 28682239, 2017). "A Pearson correlation analysis was performed to identify altered endocrine hormone expression after LW-AFC treatment that was associated with cognitive impairment, neuron loss, and Aβ deposition in APP/PS1 mice." (PMID 27964740, 2016). "They nicely present data on people with DS and familial AD with either APP mutations or APP microduplication and discuss the clinical assessment of dementia in DS individuals who have baseline cognitive impairments." (PMID 27378871, 2016). "In the present study, we examined the effects of long-term oral administration of a novel Liuwei Dihuang formula (LW-AFC) on cognitive impairment, Aβ deposition, and neuronal loss in APP/PS1 mice." (PMID 27964740, 2016).
Cognitive impairment (continued). "Knockout of APP in mice demonstrated age-related cognitive deficits including impairment in conditioned avoidance and Morris Water Maze tasks, highlighting a role for APP in processes that underlie learning and memory." (PMID 27114849, 2016). "Taken together, the results of the present investigation show that LW-AFC improves cognitive impairment, and reduces Aβ deposits and neuron loss in APP/PS1 mice via modulation of the neuroendocrine immune system." (PMID 27964740, 2016). "The neurodegeneration manifests as cognitive impairment, APP upregulation, PP2A downregulation, and neuronal loss and apoptosis in the hippocampus." (PMID 25658940, 2015). "APP23 mice express APP with Swedish mutation and develop amyloid plaques late in their life, while cognitive deficits are observed in young age." (PMID 25862638, 2015). "The Aβ1–42 injection in the bilateral hippocampus of rats induces cognitive impairment, APP upregulation and neuronal loss and apoptosis in the hippocampus." (PMID 25470026, 2014). "This loss can explain the cognitive impairment of APP/PS1 observed during the ORT and the water maze task." (PMID 23601582, 2013). "Such protective action of DHA against deterioration of cognition is in agreement with previous studies in APP mouse models of AD, which develop only Aβ pathology, and with clinical trials on cognitive impairment associated with aging." (PMID 21383850, 2011). "We demonstrated that insulin-deficient diabetes in APP/PS1 transgenic mice exacerbated cognitive deficits, characterized by excessive Aβ accumulation and subsequent formation of senile plaques." (PMID 21044348, 2010). "However, AST significantly activated autophagy in hippocampal neurons of APP/PS1 mice, thereby attenuating hippocampal neuronal loss and cognitive impairment in APP/PS1 mice." (PMID 36681681, 2023). "Further investigations are necessary to examine whether cognitive impairment mediated by cholinergic alterations observed in APP/IR‐dKI mice is caused by central insulin resistance." (PMID 37822109, 2023). "In addition, overexpression of wild-type human APP in mice causes neuronal loss and cognitive impairment." (PMID 36768625, 2023). "Similarly, TLR2-deficient APP/PS1 animals show accelerated cognitive impairment and increased Aβ1-42 concentrations in the brain." (PMID 36359817, 2022). "Moreover, magnesium-l-threonate supplements reduce the enzyme β-secretase (BACE1), reducing levels of APP C-terminal fragments and free APP, reducing AD-associated cognitive impairment and synaptic loss." (PMID 36105221, 2022). "Interestingly, another study on 4-month-old APP/PS1 mice found Aβ plaque accumulation in the hippocampus was associated with cognitive impairment and synaptic marker loss." (PMID 35966777, 2022). "As we had established that zinc deficiency could potentiate NLRP3 responses in vitro, we hypothesized that zinc deficiency accelerated cognitive impairment in the APP/PS1 mouse via the NLRP3 inflammasome." (PMID 33597269, 2021). "Since LTP remains a prominent cellular model for the persistence of long‐term memories, a more rapid decay of LTP in female APP/PS1 mice may be associated with a more severe cognitive impairment or memory loss in female AD patients." (PMID 34796608, 2021). "Compared to the APP/PS1 mice without any treatment, SZRD, especially the L-SZRD, significantly ameliorated cognitive impairment of the APP/PS1 mice with decreases in the loss of neurons and Aβ plaque deposition as well as improvement of synaptic plasticity in the hippocampus (P < 0.05 or 0.01)." (PMID 33478552, 2021). "It is likely that VX-765 may prevent an early APP mutant-mediated and Casp1-dependent deleterious neuronal pathway that causes cognitive deficits and also controls subsequent microglial activation." (PMID 32917871, 2020).
Cognitive impairment (continued). "A rat model with a doubly mutated APP, driven by a Thy1.2 promoter highly expressed in neurons, triggered the accumulation of intraneuronal human Aβ in 2–3-month-old rats, coinciding with cognitive impairments and pre-plaque generation." (PMID 31685865, 2019). "Therefore, the aim of this study was to determine if UA can rescue cognitive impairment in APP/PS1 mice and to elucidate the underlying cellular and molecular mechanisms of its effects." (PMID 30871577, 2019). "Exogenous expression of human APP and/or PSENs with disease-associated mutations in animal models leads to cognitive impairment as well as various pathological phenotypes including neuroinflammation, cellular organelle dysfunction, and impairments similar to those observed in cellular models." (PMID 30486438, 2018). "In this study, the MWM spatial memory test was used to determine whether loss of KCa3.1 had any effect on cognitive deficits in APP/PS1 mice." (PMID 30442153, 2018). "Interestingly, though APP is supposed to be critically involved in the pathophysiology of AD, APP-deficient mice exhibit cognitive deficits; this confirms that APP plays an important role in the functioning of neurons in the healthy brain." (PMID 30210311, 2018). "Interestingly, many AD transgenic mouse models carrying human APP mutation(s) display epileptiform activity and seizure susceptibility prior to amyloid plaque deposition and cognitive impairment." (PMID 28392767, 2017). "In this context, we suggest, that cognitive impairments in old APP-KO mice might be associated with an imbalanced phosphorylation-activity of the serine/threonine-specific kinases CaMKII and PKC." (PMID 28163681, 2017). "Brain injury causes cognitive impairment, increases the accumulation of amyloid precursor protein (APP), extracellular beta amyloid (Aβ) peptide and intracellular neurofibrillary tangles (NFTs) consisting of tau protein associated with inflammatory cytokine release." (PMID 29302258, 2017). "To investigate whether F. mume mitigates cognitive impairments in AD, we used 5XFAD transgenic mice co-overexpressing human amyloid precursor protein (APP) and presenilin-1 (PS1) with five familial AD (FAD) mutations." (PMID 26852239, 2016). "Interestingly, reduced expression of the EphA4 receptor has been linked to cognitive impairment in a transgenic mouse model for AD overexpressing the human amyloid beta precursor protein (APP)." (PMID 25027113, 2014). "Moreover, prolonged B1R blockade enhanced the baseline levels of the memory-related Egr-1 protein in the DG, a brain region previously associated in APP mice with cognitive deficits, reduced immediate-early gene expression and altered synaptic activity." (PMID 23642031, 2013). "In addition to disease acceleration, we observed that low HZE doses are able to cause cognitive impairment as measured by contextual fear conditioning and novel object recognition in APP/PS1 tg mice." (PMID 23300905, 2012). "The reduction in AQP4 expression was found to exacerbate the accumulation of brain Aβ and cognitive deficits in the APPswe/PS1dE9 (APP/PS1) mice; moreover, the loss of perivascular AQP4 localization might lead to the pathological process of AD in the human population." (PMID 38430054, 2024). "Thus, DDB-induced attenuation in both APP and tau pathology might also contribute to the prevention of neuronal loss and synaptic degeneration and improved cognitive impairment in 3 × Tg-AD mice." (PMID 38539620, 2024). "Both experimental reports using transgenic APP mice and human brain tissue have shown that cognitive changes occur before the formation of plaques, supporting the notion that soluble forms of Aβ may cause cognitive impairment." (PMID 38339146, 2024). "Notably, increased brain transcription and increased copy numbers of APP have been linked to APP somatic gene recombination associated with sporadic AD and with DS, and could contribute to their cognitive deficits." (PMID 35762509, 2022).
Cognitive impairment (continued). "Additionally, the same study demonstrated that the loss of FFAR3 is sufficient to reverse the cognitive impairment and amyloid-β (Aβ) pathology exhibited by the Tg2576 AD mouse model, which overexpresses the amyloid precursor protein (APP) carrying the Swedish mutation." (PMID 36362376, 2022). "Notably, suppression of ATAD3A oligomerization by either heterozygous knockout or pharmacological inhibition in AD mice enhanced MAM integrity and cholesterol metabolism, suppressed APP processing, mitigated synaptic loss, and ultimately reduced AD-associated neuropathology and cognitive deficits." (PMID 35236834, 2022). "In addition to human studies supporting improvements in cognition, ashwagandha ameliorated cognitive deficits in aged transgenic mice with amyloid precursor protein (APP)/presenilin 1 (PSEN1) variants known to be associated with dementia and other animal models." (PMID 35517054, 2022). "Thus, the combined results from ASOSNCA-injected APP mice and from APP/αSyn-KO mice indicate to us that ASOSNCA might be a viable treatment option for men with AD-associated cognitive deficits." (PMID 36517890, 2022). "In addition to triggering synaptic and tau pathology chronic administration of glucocorticoids exacerbates amyloid pathology, with accelerated amyloid deposition and cognitive deficits in transgenic mice overexpressing amyloid precursor protein (APP) with familial Alzheimer’s disease mutations." (PMID 34188184, 2021). "In this study, we discovered that microglia-specific miR-146a overexpression reduced cognitive deficits in learning and memory, attenuated neuroinflammation, reduced Aβ levels, ameliorated plaque-associated neuritic pathology, and prevented neuronal loss in APP/PS1 transgenic mice." (PMID 33754051, 2021). "Thus, E2 deficiency in young APP/PS1 mice exacerbates cognitive deficits and depletes the hippocampal NSC pool in later life; this can be alleviated by E2 treatment in the early period following OVX, which prevents Aβ/p75NTR-induced NSC overproliferation and preserves telomerase activity." (PMID 32903757, 2020). "Monomeric Aβ, a cleavage product of the proteolytic processing of the amyloid protein precursor (APP) by a β- and a γ-secretase, aggregates into Aβ oligomers and finally into amyloid fibrils, which are found in AD plaques and were previously considered to be the cause of cognitive deficits." (PMID 30003517, 2019). "Moreover, we evaluated if sleep loss facilitates early cognitive impairment in young APP/PS1 mice." (PMID 30872728, 2019). "Thus, transgenic mice overexpressing APP or PSENs with fAD mutations have been widely utilized in AD research, given that they nicely recapitulate most AD-related pathologies including Aβ plaque formation and cognitive impairment." (PMID 30486438, 2018). "Therefore, our data strongly support that C/EBPβ escalates the expression of delta-secretase, and triggers APP and Tau cleavage by delta-secretase, ultimately leading to neuronal cell loss and earlier onset of AD-like pathogenesis in 3xTg and exacerbation of cognitive impairments." (PMID 29725016, 2018). "Because APP processing leads to elevated production and accumulation of Aβ in the brain and is accelerated by Aβ1–42 injections, we hypothesized that the SM70EE-induced amelioration of the cognitive impairments observed here were associated with the regulation of APP processing." (PMID 29137190, 2017). "Tg2576 mice carry a transgene with mutations at amino acids 670 and 671 in the human APP gene under the control of the hamster prion promoter, which leads to the accumulation of Aβ plaques in the brain from 9 to 12 months of age with consequent cognitive impairment." (PMID 26305888, 2015). "Therefore, we determined whether genetic deletion of AQP4 in APP/PS1 mice advanced cognitive impairment was associated with more severe impairment of SYP and PSD-95." (PMID 26526066, 2015).
Cognitive impairment (continued). "Thus, such APP/Aβ intracellular immunoreactivity has been linked to the first cognitive deficits." (PMID 23894463, 2013). "Thus, disturbance in calcium homeostasis may provide a mechanistic link between ischemia and neurodegeneration, and may underlie the observed synergistic interaction between APP overexpression and hypoperfusion in cognitive impairment induction." (PMID 21305033, 2011). "This design allowed us to investigate both the long-term therapeutic impact of TUDCA and the progression of cognitive deficits in APP/PS1 mice." (PMID 41614917, 2026). "In a different model, the APP knock-in mice, the induction of Nrf2 ameliorated cognitive impairment, suppressing oxidative stress and decreasing neuroinflammation)." (PMID 40722916, 2025). "It is crucial to note that, while L-lactate promoted APP lactylation and ameliorated cognitive deficits in AD model mice, its effects were broad spectrum and double sided." (PMID 39744941, 2025). "This dysregulation contributes to synaptic dysfunction, cognitive deficits, and abnormal amyloid precursor protein (APP) processing." (PMID 40278152, 2025). "Excess copper primarily exacerbates cognitive impairment by increasing the expression of amyloid precursor protein (APP) and β-site APP cleaving enzyme 1 (BACE1), promoting the accumulation of amyloid β (Aβ)." (PMID 40510202, 2025). "First, we performed behavioral tests to examine the impact of BGP-15 on cognitive deficits in APP/PS1 mice." (PMID 40354372, 2025). "This study found that LGZG administration ameliorates cognitive impairment in APP/PS1 transgenic mice." (PMID 39911633, 2025). "Studies have shown that moxibustion at CV4 (Guanyuan) and moxa smoke exposure both ameliorated cognitive deficits in APP/PS1 mice by normalizing tricarboxylic acid cycle flux and unsaturated fatty acid metabolism." (PMID 40357233, 2025). "TMAO levels are significantly elevated in AD patients, and studies demonstrate that plasma TMAO concentrations greater than five μM correlate with faster hippocampal atrophy, cognitive deficits, and microglial activation in humans and in APP/PS1 mouse models." (PMID 41299728, 2025). "Protein- and gene-level studies further clarified how CBM588 improves cognitive impairment in APP/PS1 mice via the MGBA." (PMID 40621927, 2025). "The improvements in spatial memory and LTP following PU-AD treatment in APP NL-F mice provide strong evidence confirming the direct role of epichaperomes in driving synaptic dysfunction and cognitive impairment across the AD continuum." (PMID 39989971, 2025). "Our previous findings demonstrated that EA improves cognitive deficits in APP/PS1 mice by increasing LC noradrenaline synthesis via activation of the NTS-LC noradrenergic circuit." (PMID 41233833, 2025). "Investigated Mn-induced cognitive impairment mechanisms by assessing the role of APP in cognitive deficits, APP’s secretase processing in neurotoxicity, and synaptic dysfunction by using both in vivo mouse model and in vitro cell culture (N2a cells)." (PMID 40278152, 2025). "CBM 588 was used to treat APP/PS1 double transgenic mice, and its effect on cognitive impairment in APP/PS1 mice was investigated using water maze experiments." (PMID 40621927, 2025). "The age between 12 and 16 months therefore represents a potential tipping point whereby APP KI mice display age- and genotype-dependent cognitive impairment, an essential parameter for the study of disease modifying factors of amyloid pathology." (PMID 39920176, 2025). "It has also been reported that AlCl3 treatment down-regulated DNA methylation-related genes in mice, reduced the hypomethylation of the APP, up-regulated its expression, and promoted amyloid accumulation, leading to cognitive impairment." (PMID 39997934, 2025).